TNF (tumor necrosis factor)
Diseases named in the same sentence as TNF in open-access papers (continued):
Sharing a sentence is not in itself a finding about the gene and the disease.
aortitis (4 papers, 2019 to 2025). Inflammation of the aorta. "In GPA and MPA, PR3-ANCA or MPO-ANCA-mediated neutrophil activation causes aortitis by releasing cytokines (e.g., tumor necrosis factor (TNF)-alpha and IL-1) and matrix metalloproteinases (MMPs) that degrade elastin and collagen in the aortic media, weakening the vessel wall." (PMID 40535417, 2025). "While the efficacy of anti-TNF treatments on macrovascular complications (e.g., aortitis) has been more thoroughly investigated in the literature, few data are available on their effects at the microvascular level." (PMID 40075844, 2025). "DC-derived IL-1β and macrophage-derived TNF are thought to subsequently activate Th17 cells to induce IL-17, contributing to development of aortitis in Il1rn−/− mice." (PMID 31745167, 2019). "Regarding this, using bone marrow cell transfer analysis, we showed that IL-25 derived from non-hematopoietic cells rather than immune cells was crucial for development of IL-1–, TNF– and IL-17–mediated aortitis in Il1rn−/− mice." (PMID 31745167, 2019). "In the present study, we demonstrated that IL-25 is crucial for development of IL-1–, TNF– and IL-17–mediated aortitis in Il1rn−/− mice." (PMID 31745167, 2019). "The development of aortitis in Il1rn−/− mice is dependent mainly on IL-1 and TNF, and at least in part on IL-17A22,23." (PMID 31745167, 2019). "Here, we demonstrate that IL-25 plays a facilitative role in the development of IL-1–, TNF– and IL-17A–mediated aortitis in Il1rn−/− mice." (PMID 31745167, 2019). "Mice deficient in IL-1 receptor antagonist (Il1rn−/− mice) have excessive IL-1 signaling, resulting in spontaneous development of IL-1–, TNF– and IL-17A–dependent aortitis." (PMID 31745167, 2019). "IL-25 enhanced IL-1β and TNF production by IL-25 receptor–expressing dendritic cells and macrophages, respectively, at inflammatory sites of aortae of Il1rn−/− mice, contributing to exacerbation of development of IL-1–, TNF– and IL-17A–dependent aortitis in those mice." (PMID 31745167, 2019). "The spontaneous development of aortitis in those Il1rn−/− mice was dependent on T cells, whereas it was suppressed by deficiency of TNF-α or IL-17A, but not IL-622,23." (PMID 31745167, 2019). "However, the role of IL-25 in IL-1–, TNF– and IL-17A–mediated aortitis in Il1rn−/− mice has been unclear." (PMID 31745167, 2019). "We found that expression of II25 mRNA was increased in the aortae of Il1rn−/− mice, suggesting that IL-25 may suppress development of IL-1–, TNF– and IL-17A–dependent aortitis in Il1rn−/− mice by inhibiting type 3-mediated immune responses." (PMID 31745167, 2019). "It was reported that the development of aortitis was diminished in Il1r1−/−Il1rn−/− mice and Tnfa−/−Il1rn−/− mice, whereas it was normal in Il6−/−Il1rn−/− mice, indicating that IL-1α and/or IL-1β, and TNF are crucial for development of aortitis in Il1rn−/− mice." (PMID 31745167, 2019). "In aortitis, PR3-ANCA triggers neutrophil degranulation, releasing cytokines (e.g., TNF-alpha and IL-1) and MMPs that degrade elastin and collagen in the aortic media, causing inflammatory weakening." (PMID 40535417, 2025). "On the other hand, our results suggest that IL-25 may enhance production of IL-6, IL-17A and TNF, but not IL-23, thereby contributing to development of IL-1–, TNF– and IL-17A–dependent aortitis in Il1rn−/− mice." (PMID 31745167, 2019). "However, Il25−/−Il1rn−/− mice showed attenuated development of aortitis compared with Il1rn−/− mice, indicating that IL-25 contributed to exacerbation—not suppression—of IL-1–, TNF– and IL-17–mediated aortitis in Il1rn−/− mice." (PMID 31745167, 2019).
articular cartilage disorder (4 papers, 2013 to 2023). A disease involving the articular cartilage of joint. "Novel treatment options for more advanced disease in patients with costochondritis associated with important lethal syndromes are proposed like anti-tumor necrosis factor treatment with adalimumab and anti-interleukin-6 receptor antibody." (PMID 24416624, 2013). "Moreover, some common causal genes have been demonstrated in different types of chondropathies, such as tumor necrosis factor α (TNF-α) and interleukin 1β (IL-1β)." (PMID 31455417, 2019).
astroglioma (4 papers, 2006 to 2025). "A growing body of evidence highlights the regulatory role of microRNAs (miRNAs) in modulating TNF-α and IL-1β signaling in astrocytic tumors." (PMID 40565357, 2025). "This study provides an integrative, multi-omic evaluation of TNF-α signaling in astrocytic tumors, revealing significant correlations between pathway activation, molecular regulation, and clinical outcome." (PMID 40565357, 2025). "Our findings establish a multi-layered regulatory mechanism of TNF-α signaling in astrocytic tumors." (PMID 40565357, 2025). "In this work, we induced the generation of A1-like reactive astrocytes after the co-treatment of U251 human astroglioma cells with a cocktail of the cytokines TNF-α, IL1-α and C1q." (PMID 37513235, 2023). "In a previous study we showed marked up-regulation of MCP-1 expression and secretion by astroglioma cells after TNF treatment." (PMID 16987412, 2006). "Out of 119 genes associated with TNF-α-dependent signaling, one-way ANOVA revealed that six genes were significantly differentially expressed (fold change > 5.0 or <–5.0; p < 0.05) in G3 and G4 astrocytic tumors relative to G2." (PMID 40565357, 2025). "Therefore, the aim of this study was to evaluate variations in the expression patterns of TNF-α-related inflammatory mediators and their regulatory microRNAs in astrocytic tumors of varying malignancy grades." (PMID 40565357, 2025). "To investigate potential epigenetic regulation of inflammatory mediators, we analyzed the promoter methylation status of TNF-α, IL-1β, MAP3K8, and MAP2K7 in astrocytic tumors across different malignancy grades." (PMID 40565357, 2025).
Bell's palsy (4 papers, 2021 to 2024). Partial or complete paralysis of the facial muscles of one side of a person's face. "The measurements of the serum samples from patients with Bell’s palsy showed significantly higher levels of IL-6, IL-8, and TNF-α in patients with Bell’s palsy compared to controls." (PMID 38689877, 2024). "Elevated cytokines (IL-1, IL-6) and tumour necrosis factor (TNF a) were found in the patients with Bell's Palsy in comparison to a control group." (PMID 36212732, 2022). "Evaluation of patients with Bell’s palsy has shown the increase in serum levels of IL1, IL6, and TNF-alpha (Tumor Necrozing Factor) compared to healthy individuals, representing the activities of the cell-mediated immune system’s operative factors." (PMID 35474925, 2021). "It was already well established that IL6, IL8 and TNF-alpha levels were significantly higher in Bell’s palsy, but serum levels of these cytokines do not help to determine the prognosis in Bell’s palsy." (PMID 35474925, 2021).
bladder urothelial carcinoma (4 papers, 2008 to 2024). "IL-10 is a suppressor of TNF-α synthesis and a potent anti-inflammatory cytokine that is present at the sites of tumors in a wide variety of human cancers, including transitional cell carcinoma of the bladder." (PMID 19040745, 2008). "Interestingly, similar mycoplasma microbiome signatures and clinical data were also observed in the high TNF mRNA group in patients with different types of tumors, such as uterine corpus endometrial carcinoma and bladder urothelial carcinoma." (PMID 37867861, 2023).
Blindness (4 papers, 2021 to 2023). Blindness is the condition of lacking visual perception defined as a profound reduction in visual perception. "Fortunately, the use of biologics, particularly TNF-α targeting monoclonal antibodies, have been shown to mitigate ocular inflammation and prevent blindness to a certain degree." (PMID 36192768, 2022). "TGF-β/TNF-α–induced RPE-EMT induces epigenomic changes and leads to fibrous epiretinal membranes that are similar to those observed with severe blinding disease conditions." (PMID 33792620, 2021). "Biological drugs, especially those targeting anti-tumour necrosis factor α (TNFα) molecule, have revolutionized the treatment of patients with non-infectious uveitis (NIU), a sight-threatening condition characterized by ocular inflammation that can lead to severe vision threatening and blindness." (PMID 36986627, 2023).
bovine tuberculosis (4 papers, 2016 to 2023). "For instance, calves typically infected with bovine tuberculosis had a predominance of TNF-α+IFN-γ+IL-2+ and TNF-α+IFN-γ+IL-2− CD4+ T cells with a TEM phenotype." (PMID 36960295, 2023). "Because TNF-a is crucial in restricting the growth of M. tuberculosis, we speculated that the 108-bp INS in the SPN gene was related to the low susceptibility of indicine cattle to bovine tuberculosis." (PMID 37723525, 2023). "Inhibition of CD244 expression may promote the expression of IFN-γ/TNF-α in CD8+ T cells and may reduce the incidence and mortality of bovine tuberculosis." (PMID 32153632, 2020).
bullous keratopathy (4 papers, 2014 to 2023). "Serum TNF-α concentration among patients with bullous pemphigoid was 402.51 pg/ml, which is significantly higher than that among healthy controls (111.47 pg/ml)." (PMID 30473747, 2018). "The findings of the present study demonstrate increased expression of TNFα in skin lesions, both in the case of bullous pemphigoid and in dermatitis herpetiformis." (PMID 25400334, 2014). "It has already been proven that the levels of some proinflammatory cytokines, such as interleukin (IL)-1a, IL-6 IL-8, IL-17a, TNF-alpha, and IFN-c, were higher in the aqueous humor of eyes with bullous keratopathy and a low density of ECs." (PMID 36968840, 2023). "Our results demonstrated that CD55 was downregulated by TNF-α and IFN-γ via the ERK1/2 pathway, clarifying the involvement of abnormal complement activation in bullous pemphigoid pathogenesis." (PMID 30473747, 2018). "Notably, a significant increase in the expression of TNF-α and IFN-γ, administration of which downregulated CD55 levels in HaCaT cells, was observed in the sera of patients with bullous pemphigoid (n = 38) compared to that in healthy controls (n = 19)." (PMID 30473747, 2018). "In addition, elevated TNF-α and IFN-γ levels in patients with bullous pemphigoid downregulated CD55 via activation of ERK1/2 signaling." (PMID 30473747, 2018).
cerebral small vessel disease (4 papers, 2021 to 2026). Cerebral small vessel disease is the term currently used to pathological processes that affect the brain parenchymal circulation (arterioles, capillaries, and veins). "A study demonstrated that increased IL‐1β and TNF‐α expressions were observed in the hippocampus of a rat cerebral small vessel disease model." (PMID 34586752, 2021). "Cerebral small vessel disease causes blood–brain barrier (BBB) functional damage, chronic inflammation such as the increased IL‐1β and TNF‐α expression, and leukocyte infiltration, leading to the development of neuron and oligodendrocyte injury." (PMID 34586752, 2021). "Cerebral small vessel disease (CSVD) may benefit from anti-inflammatory therapy, as age-related inflammation—mediators such as TNF, caspase-1, IL-1β, and the NLRP3 inflammasome—is considered a risk factor." (PMID 40017533, 2025).
cervical spondylosis (4 papers, 2023 to 2025). "Tumor necrosis factor alpha (TNF-α) adversely mediates bone degradation by facilitating matrix degradation, which exacerbates cervical spondylosis." (PMID 37371064, 2023).
Cholecystitis (4 papers, 2020 to 2025). The presence of inflammatory changes in the gallbladder. "In case of severe inflammatory response, both IL-6 and TNF-α activate the coagulation cascade, explaining the presence of thrombosed vessels in the gallbladder and the occurrence of an ischemic gangrenous cholecystitis." (PMID 32615987, 2020). "While the precise correlation between cholecystitis and GBC remains unclear, a proposed mechanism involves recurrent acute cholecystitis, leading to the release of pro-inflammatory cytokines such as IL-1, IL-6, and tumour necrosis factor-alpha (TNF-α)." (PMID 40142228, 2025).
Cholestatic liver disease (4 papers, 2014 to 2026). "In cholestatic liver disease, hepatocytes are exposed to inflammation (TNF-α production by Kupffer cells) and increased oxidative stress (e.g. mitochondrial dysfunction and/or infiltrating neutrophils)." (PMID 26950211, 2016). "Additionally, the estrogen, tumor necrosis factor-alpha, and VEGF signaling pathways were enriched in cholestatic liver disease." (PMID 41758906, 2026).
chorioretinitis (4 papers, 2017 to 2025). Inflammation of the distal posterior uveal tract (choroid) and its structural and vascular attachments to the retina. "This is supported by studies showing that TNF-α neutralisation increases susceptibility and parasite burden and that elevated TNF-α levels have been reported in retinochoroiditis associated with congenital toxoplasmosis." (PMID 41011132, 2025).
chronic asthma (4 papers, 2012 to 2025). An asthma that is characterized by the development of persistent airway inflammation and recurrent attacks of breathlessness and wheezing, which vary in severity and frequency. "This is in agreement with the results of prior studies on OVA-mediated chronic asthma models, and further indicates that rosuvastatin treatment leads to a significant decrease of not only Th2 cytokines, but also other mediators, including TNF-α, MMP9, and TGF-β1." (PMID 38913666, 2024). "Both fungal extracts significantly elevated the IL-4, IL-5, IL-13, TNF-α, and TGF-β levels in mice with acute and chronic asthma." (PMID 40558541, 2025).
chronic headache (4 papers, 2014 to 2022). "The authors suggest that the persistent elevation of TNF-α in the CSF may be one of the causes of treatment-refractory chronic headache." (PMID 36614097, 2022). "In the current study, TNF-α was found to be a protective factor for post-TBI chronic headache, which was supported by a number of previous studies." (PMID 35815027, 2022). "Acupuncture significantly reduces plasma levels of TNF-α in patients with chronic headache and mRNA levels of IL-6 and IL-1β in rats of lipopolysaccharide-induced fever." (PMID 24991226, 2014). "TNF-α was identified as a protective factor for post-TBI chronic headache (OR = 0.473)." (PMID 35815027, 2022). "TNF-α was a protective factor for chronic headache (OR = 0.473, 95% CI = 0.235–0.952)." (PMID 35815027, 2022).
chronic inflammatory demyelinating polyneuropathy (4 papers, 2013 to 2021). "Two patients have been described who developed a chronic inflammatory demyelinating polyneuropathy during their course of therapy with TNF-alpha antagonists." (PMID 23573450, 2013).
chronic spontaneous urticaria (4 papers, 2019 to 2025). "However, the role of the TNF-α system and Fas/Fas ligand (FasL) in the apoptosis-inducing pathways in chronic spontaneous urticaria (CSU), remain unclear." (PMID 30911316, 2019).
chronic tonsillitis (4 papers, 2020 to 2025). "In conclusion, our study has seen an association between vitamin D intake and the levels of TNF-α, some interleukins, and CD68 expression in children with chronic tonsillitis." (PMID 37198277, 2023). "Pediatric SDB is related to chronic inflammatory condition such as chronic tonsillitis and chronic adenoiditis, with raised in various inflammatory mediators, such as TNF-α, IL-1 and IL-6." (PMID 32393268, 2020). "Specifically, levels of TNF-α, IL-1, IL-6 are higher in the saliva of children with chronic tonsillitis, although statistically significant differences were only noted for the pro-inflammatory cytokine IL-618." (PMID 32747802, 2020).
chronic venous insufficiency (4 papers, 2005 to 2023). Chronic form of venous insufficiency (disease). "Likewise, in patients suffering from chronic venous insufficiency and treated for three months with diosmin at a total daily dose of 1200 mg, a decrease in the proinflammatory factors TNF-α, IL-6, VEGF-A, and VEGF-C, which were associated with a reduction in mean leg circumference, was observed." (PMID 37513462, 2023).
clostridium difficile infection (4 papers, 2019 to 2025). Symptomatic infection due to the spore-forming bacterium clostridium difficile. "After receiving anti-TNFα and 12 further doses of ICI with no disease progression, Patient 1 developed a Clostridium difficile infection after which he had recurrence of irEC." (PMID 31439050, 2019).
colonic polyps (4 papers, 2011 to 2024). "Innate immune response-related pathways and processes, such as leukocyte chemotaxis, cytokine production, IL-17, TNF, IL-1 and NF-kB signaling pathways, were prominently enhanced in CCS colonic polyps." (PMID 38297356, 2024).
common variable immunodeficiency (4 papers, 2014 to 2025). "Low dose Ig or IRT has also been shown to decrease production of pro-inflammatory cytokines such as IL-2, IL-12, and TNF-α by monocytes in common variable immunodeficiency (CVID) patients." (PMID 31613907, 2019).
Cough (4 papers, 2015 to 2025). A sudden, audible expulsion of air from the lungs through a partially closed glottis, preceded by inhalation. "Therefore, airway activated IFN‐γ+ T‐lymphocytes and dysregulated cytokines (especially IFN‐γ, TNF‐α, IFN‐α, IFN‐β, and IL‐10) might serve as inflammatory signatures in some patients with postinfectious cough." (PMID 40859955, 2025).
cutaneous sarcoidosis (4 papers, 2011 to 2023). "Summary of clinical outcomes for refractory cutaneous sarcoidosis treated with TNF-α and JAK/STAT inhibitors." (PMID 37818515, 2023). "Recently, monoclonal antibodies inhibiting interleukin 12, interleukin 23, and tumor necrosis factor alpha have been tested in patients with lung and/or skin sarcoidosis, however, the superiority of this treatment compared with steroids is unclear." (PMID 25329890, 2014). "There is clinical evidence that inhibition of TNF-alpha is an effective therapy for treating both systemic and cutaneous sarcoidosis which is consistent the view that TNF-alpha plays a prominent role in the inflammatory process seen in these conditions." (PMID 21603192, 2011). "Taken together, these observations are consistent with the hypothesis, that both increased risk of skin infections and alterations in the skin immunological microenvironment may be responsible for the paradoxical occurrence of cutaneous sarcoidosis during treatment with TNF-blockers." (PMID 21603192, 2011). "Although to date no studies have investigated the expression of these cytokines in cutaneous sarcoidosis, there is clinical evidence indicating a role for some cytokines associated with a Th1 immune response, notably interferon (IFN) alpha and tumor necrosis factor (TNF) alpha." (PMID 21603192, 2011). "Studies on anti-JAK-STAT interventions demonstrate no adverse events after treatment; however, patient study size was limiting.Recent studies have shown promising potential for anti-TNF-α and anti-JAK-STAT inhibitors to become the mainstay interventions in refractory cutaneous sarcoidosis." (PMID 37818515, 2023). "TNF-α: Tumor Necrosis Factor-alpha (infliximab and adalimumab); JAK-STAT: Janus kinase/Signalling transducer of activators of transcription (ruxolitinib and tofacitinib); CS: Cutaneous sarcoidosis; CSAMI: Cutaneous Sarcoidosis Activity and Morphology Instrument." (PMID 37818515, 2023).
deficiencies (4 papers, 2012 to 2025). "Additionally, PD-1 inhibition has been associated with increased production of pro-inflammatory cytokines, particularly interferon-gamma (IFN-gamma) and tumor necrosis factor-alpha (TNF-alpha), which can disrupt the function of pituitary cells and contribute to irreversible hormone deficiencies." (PMID 40416222, 2025). "Since no studies regarding the relationship between the studied SNP and nutritional deficiencies have been published yet, we decided to confront our results with those available for other SNPs with emphasis on those located in genes encoding proteins of the TNF–TNF-R axis." (PMID 35884467, 2022).